TLR3 (toll like receptor 3)
Diseases named in the same sentence as TLR3 in open-access papers (continued):
Sharing a sentence is not in itself a finding about the gene and the disease.
viral infection (continued). "Our results suggest that vitamin D3 may play a protective role in the development of exacerbations due to viral infections, by its ability to regulate TLR3 responses in BSMCs." (PMID 34512638, 2021). "Toll-like receptor 3 (TLR3) meanwhile, is expressed in the cytoplasm or in the membrane of endosomes where it detects strings of nucleotides indicative of a viral infection." (PMID 33585492, 2021). "In addition, a role linked to viral infection was suggested for APOL1 and APOL3, given the strong induction of their expression through the viral inflammatory TLR3/TRIF pathway, and the linkage of G1‐ or G2‐induced kidney disease with HIV infection." (PMID 32530132, 2021). "Another example, biallelic loss of functions mutations in gene DBR1, (encoding RNA lariat debranching enzyme) which functions in hydrolyzing 2′-to 5′ branches phosphodiester bonds of intron RNA, led to impaired HSV-1 viral infection in the brainstem in a TLR3 independent manner." (PMID 33498715, 2021). "Also, OEC-mediated T cell suppression was limited when stimulating OECs with poly(I:C), a TLR3 agonist, emulating a viral infection." (PMID 35126344, 2021). "Both viral infection and histamine treatment upregulated TLR3 and TLR7 expression." (PMID 34214498, 2021). "It is likely, therefore, that the elevated expression of TLR3 may contribute to an improvement in the host defense against viral disease." (PMID 33152221, 2021). "We share the point of view that during viral infection, naked viral dsRNA reaches extracellular milieu following lysis of the infected cells, and TLR3 requires the internalization of RNA for sensing through an endocytic pathway." (PMID 33281554, 2020). "Stimulation of MDMs with the TLR1/TLR2 agonist (mimicking bacterial infection) resulted in a strong increase of CD127 expression, comparable to that after LPS exposure, whereas no relevant induction of CD127 was observed after stimulation with the TLR3 agonist (mimicking viral infection)." (PMID 33584648, 2020). "The TLR3 SNP rs3775296 was significantly associated with HTLV-1 infection and may be a protective factor against this viral infection." (PMID 32578708, 2020). "In this study, CASP8, IL22 and TLR3 were chosen to be used as target genes to assess the performance of the shortlisted reference genes, because these three genes play important roles in the innate immune response against virus infection." (PMID 32444639, 2020). "It has been posed that the difference in TLR3-mediated protection against viral infection compared to bacterial infection may be due to the production of type I IFNs which impairs bacterial clearance." (PMID 33679711, 2020). "TLR3 signaling is important for interferon-α/β mediated induction of ISGs and has been reported in several fish species including rainbow trout upon either poly(I:C) stimulation or viral infection (both dsRNA and ssRNA viruses)." (PMID 32922394, 2020). "Moreover, the CRL1505 strain has been shown to beneficially modulate the antiviral innate immune response triggered by TLR3 activation in mice and reducing the severity of viral infections in children." (PMID 32508770, 2020). "TLR3 is involved in the sensing of dsRNA, the replication intermediate of many DNA and RNA viruses, and regulates immunity to most of the clinically important viral infections in humans." (PMID 33281554, 2020). "Toll-like receptors (TLRs) are innate immune-recognition receptors known to play a role in viral infection, and TLR3, which recognizes and responds to dsRNA, was found to be required for the induction of proinflammatory factors and disease exacerbation in leishmaniasis." (PMID 32873760, 2020). "Given TLR3 recognizes viral RNA, this pathway may have implications in other viral infections that target the pulmonary epithelium." (PMID 31416461, 2019). "Among them, TLR3 has been considered as the major mediator against virus infection." (PMID 31889912, 2019).
viral infection (continued). "On the other hand, the use of agonists of TLR3, a receptor that recognizes pathogen or host double-stranded RNA (dsRNA) that may be produced during viral infections or abnormal cellular processes, has been reported to promote effective antiviral responses." (PMID 31114761, 2019). "In herpes simplex epithelial keratitis, excessive TLR3-induced cellular responses after virus infection evoke inflammatory cascades that might be destructive to the host cornea." (PMID 31889912, 2019). "In addition to IAV, there are other examples of SNPs in TLR3 or TLR3 signaling genes affecting viral infections." (PMID 31574965, 2019). "Furthermore, the effects of oxidative stress (H2O2) and Toll like receptor 3 (TLR3) ligand poly (I:C) (mimicking viral infection) on the levels of very large lncRNAs were also evaluated in human monocytic cell line THP-1 and glioma cell line KALS1." (PMID 30119681, 2018). "TLRs 1, 2, 6, and 10 recognize bacterial lipoproteins; TLRs 4 and 5 recognize LPS and flagellin, respectively; TLRs 7, 8, and 9 recognize nucleic acid molecules; TLRs 10, 11, and 12 recognize actin-like molecules; and TLR3 recognizes dsRNA, an intermediate generated during most viral infections." (PMID 29264743, 2018). "Similarly, the expression of the chemokines Cxcl9 and Cxcl10 by TLR3 tolerized macrophages correlates with the role of these factors in CD8+ T cell recruitment to sites of viral infection, cells that have a critical anti-viral activity." (PMID 29867935, 2018). "Chemokine CXCL10 was selected as known to be induced by TLR-3 activation in viral infections." (PMID 29361613, 2018). "Although, it has been shown that double stranded (ds) RNA can be used for the stimulation of TLR3 signaling pathway in a number of host-viral infection models, it’s effectiveness as an antiviral agent against low pathogenic avian influenza virus (LPAIV) needs further investigation." (PMID 29530062, 2018). "TBK1 was initially identified in the context of its ability to regulate NF-κB in vitro, yet later studies in TBK1 deficient mice demonstrated that TBK1 is an essential component of the IRF3 signaling pathway after both viral infection and stimulation of TLR3 by dsRNA31." (PMID 29343779, 2018). "TLR3 primarily protects the heart against viral infection; however, TLR3 also mediates inflammatory effects that may exacerbate heart damage." (PMID 29576748, 2018). "However, MyD88 was up-regulated upon viral infection, because all other members of TLRs family, except for TLR3, can be activated by MyD88 dependence." (PMID 30151032, 2018). "First, TLR3 is responsible for immuneresponses against viral infections." (PMID 28836400, 2017). "The relationship between TLR3 and viral infection is highly complex and virus-specific." (PMID 28046022, 2017). "We next examined whether the viral infection-impaired GC action was mediated by activation of TLR3 using targeted siRNA." (PMID 28046097, 2017). "TLR3 is an important sensor of viral infections and it was recently shown that neonatal TLR3 activation results in altered plasticity of dendritic spines several weeks later (at P21), suggesting a long-lasting effect of TLR3 activation on spinogenesis." (PMID 28744200, 2017). "Effects of maternal infection on fetal central inflammatory responses are age-dependent as shown by differently expressed cytokines in the fetal brain and brain pathology following poly(I:C) (a TLR3 agonist that mimics viral infections) injected at embryonic day (E) 9 compared to E17 in mice." (PMID 28744200, 2017). "TLR3 plays an important role in IFN-mediated innate immunity against many virus infections." (PMID 28234991, 2017). "The IEC senses viral dsRNA through pattern recognition receptors (PRRs), such as TLR3, retinoic acid-inducible gene-I (RIG-I), and melanoma differentiation-associated gene-5 (MDA-5), and cellular signaling cascades are activated to react to viral infection." (PMID 27994593, 2016).
viral infection (continued). "Thus, dual capacity of induction of mucosal IgA responses and protection against viral infection should be taken into consideration when selecting detoxified TLR3 agonist as safe anti-infectious vaccine adjuvants for human use." (PMID 29263853, 2016). "PIC mimics viral infection via binding to TLR3 and results in an inflammatory response." (PMID 27955671, 2016). "Moreover, A20 knock down results in enhanced IRF3-dependent transcription triggered by the stimulation of TLR3 or virus infection." (PMID 27994593, 2016). "It is known that TLR3, 7, 8, 941 recognize and respond to viral infections, inducing IFNs and ISGs." (PMID 27734899, 2016). "Recently, we and others have shown that viral infection and the stimulation of TLR3 induces the expression and production of MUC5AC in airway epithelial cells mainly via epidermal growth factor receptor (EGFR) and extracellular signal-regulated kinase (ERK) signaling pathways." (PMID 27677339, 2016). "Importantly, knocking down of A20 expression results in enhanced IRF-3-dependent transcription triggered by the stimulation of TLR3 or virus infection." (PMID 27023883, 2016). "Viral infection activates IFN production through TLR3 in almost all types of cells." (PMID 28163697, 2016). "Poly(I:C), which mimics viral infection, is recognized by TLR3 and RIG-I16." (PMID 27270888, 2016). "TLR3 signaling plays a well-established and vital protective role in many viral infections." (PMID 27504984, 2016). "Furthermore, monitoring of virus infection using a firefly luciferase (FLuc)-tagged recombinant CHIKV (FLuc-CHIKV) revealed increased CHIKV dissemination in Tlr3−/− mice." (PMID 25452586, 2015). "Probably, fish TLR22 may be a functional substitute for human cells surface TLR3 for detecting dsRNA virus infection." (PMID 25759845, 2015). "In addition, the viral infection provoked the activation of several PRRs including TLR3, TLR7, TLR22, MDA5, and LGP2a and b." (PMID 25338079, 2014). "Further investigation of the function of TLR3 on qHSC may therefore lead to strategies for modulating the recruitment and activation of innate immune cells during acute viral infections and drug-induced liver injuries." (PMID 24416163, 2014). "Although we focused on TLR3-mediated cellular and molecular events in the olfactory mucosa, real viral infections can induce other innate immune responses and adaptive immune responses which could also contribute to tissue damage." (PMID 24744264, 2014). "Toll-like receptor 3 recognizes double-stranded RNA during viral infections." (PMID 25539593, 2014). "However, the functional role of cell surface TLR3 in mediating immune response to viral infections still needs to be resolved." (PMID 24651829, 2014). "It is known that TLR3 has a complex role in viral infections." (PMID 24860569, 2014). "In addition to several cell lines that constitutively express TLR3 at the plasma membrane, cell surface localization of TLR3 is also induced by the viral infection." (PMID 24651829, 2014). "Therefore some groups have used poly(I:C), a synthetic analogue of double-stranded RNA which activates TLR3 (Toll-like receptor 3), to simulate viral infections and to model COPD acute exacerbation-like changes." (PMID 24144354, 2014). "To determine if the increased susceptibility to viral infection of the IL-21R KO mice could be due to an inherent altered expression of PRRs we measured mRNA levels of TLR2, TLR3, TLR9, MDA-5, AIM-2, DAI, RIG-I and IFI16." (PMID 24358128, 2013). "Trophoblasts, which express TLR3, play a role in coordinating the maternal innate immune response to infection at the fetomaternal interface and, especially in this case, in response to viral infection." (PMID 24174710, 2013). "Finally, polyinosinic-polycytidylic acid (polyI:C), a synthetic analog of double-stranded RNA, was chosen to mimic viral infection (TLR3 agonist, although it can also stimulate RIG-I and MDA5)." (PMID 23844079, 2013).
viral infection (continued). "Several factors might contribute to the observed differences in the effect of Tlr3 on disease outcome after viral infection." (PMID 22570612, 2012). "Therefore, our current results strongly warrant caution on the use of TLR3-mediated immune interventions against chronic viral diseases and suggest careful consideration for these treatments in conjunction with the time of viral infection." (PMID 22189096, 2011). "Both TLR3- and MDA5-mediated type I IFN signaling have been implicated in the response to CVB3 infections and mice deficient in either TRIF or MAVS show an enhanced susceptibility to viral infection." (PMID 21436888, 2011). "To determine whether LL37 can affect TLR3-mediated responses to viral infections, we infected BEAS2B cells with RV in the presence or absence of LL37." (PMID 22039520, 2011). "However, no further studies have been performed regarding the functional role of TLR3 in the immune responses against porcine viral diseases." (PMID 22046952, 2011). "Studies have shown that TLR3 plays a protective role against various viral infections in vivo." (PMID 21637773, 2011). "Therefore, the efficacy of TLR3-mediated protection from acute viral infection appears to be limited to a narrow time window." (PMID 22189096, 2011). "Moreover, TLR3 knock-out mice have an impaired response to cytomegalovirus infection, suggesting that TLR3 plays an important role in the defense against viral infection." (PMID 22039520, 2011). "Interestingly, premature activation of TLR3 via administration of poly IC prior to viral infection promoted disease progression." (PMID 22189096, 2011). "Toll-like Receptor 3 (TLR3) detects viral dsRNA during viral infection." (PMID 22039520, 2011). "However, activation of TLR3 with poly IC prior to viral infection also exacerbated disease development, whereas such activation after viral infection restrained disease development." (PMID 22189096, 2011). "In contrast, premature activation of TLR3 signal transduction prior to viral infection may induce premature stimulation of regulatory immune mechanisms, hindering anti-viral immune cell function and promoting viral persistence." (PMID 22189096, 2011). "Moreover, it was shown that TLR3 is able to mediate harmful inflammatory responses in the intestine, thus contributing to the pathogenesis of viral infections." (PMID 22046952, 2011). "Since TLR3 is activated during viral infection, additional co-factors may be needed to enhance the ability of TLR3 to recognize viral dsRNAs during infection." (PMID 22039520, 2011). "A major function of TLR3 is to sense and respond to viral infection." (PMID 19247444, 2009). "The high levels of TLR3 in the CNS suggests an important role in the response to neuronal injury and/or viral infection, which may involve mechanisms other than those limited to the innate immune response." (PMID 19247444, 2009). "It is tempting to speculate in whether TLR3 is yet another way for CD8+ T cells to recognize viral infections, and thus have a role in activation of the cytotoxic T cell response." (PMID 16504163, 2006). "TLR3 thus plays an important role in host defense against viral infections." (PMID 15921526, 2005). "Nevertheless, an analysis using multiple logistic regression of the variables examined in relation to HTLV-1-associated disease symptoms indicated that the TLR3 rs3775291 C/T polymorphism was not linked to clinical manifestations resulting from viral infection." (PMID 40831704, 2025). "As a TLR3 agonist, Poly I:C has been shown to enhance interferon responses during viral infection; we further hypothesized that giving Poly I:C after the infection serves as a therapeutic approach working to reduce the severity of respiratory viral infection in IP KO mice." (PMID 39339860, 2024). "Consequently, immune responses, mediated by TLR3 in teleosts, may be crucial in viral infections as in mammals." (PMID 36670828, 2023).
viral infection (continued). "Our results indicate that in contrast to TLR3 stimulation of unprimed skin fibroblasts, TLR3 stimulation of NDAS patient hematopoietic cells with poly(I:C) or by viral infection may lead to enhanced type I IFN production and antiviral responses due to a relatively stabilized NEMO-Δex5-IKKi complex." (PMID 35289316, 2022). "Besides, TLR3 detects viral infection and triggers an innate immunity signaling pathway." (PMID 35990651, 2022). "However, unlike in the cells treated with siRNAs alone, at the latest time point of the treatments involving virus infection, the mRNA levels of MxB and TLR3 were significantly different from mock treatment, when subjected to the antiviral siRNAs or GFP-specific siRNA." (PMID 35793357, 2022). "Finally, a study involving different dosing regimes of hiltonol (a synthetic dsRNA complex, which stimulates TLR3), administered to mice at various times before and after exposure to MA15, supports previous findings of the protective role of TLR3 during viral infection." (PMID 33498183, 2021). "On the contrary, Emodin could decrease the mRNA and protein levels of TLR3 and downstream molecules against Coxsackievirus B3m infection, indicating that Emodin has different antiviral mechanisms involved in fighting different virus infections." (PMID 34206896, 2021). "However, cytokine signaling pathway redundancy may also be observed with respect to TLR3 activation and data are varying regarding TLR3 role in protective immunity during other viral infections." (PMID 33281554, 2020). "Although it is believed that TLR3 activation occurs entirely in acidic endosomes, perhaps it would also be beneficial for cells to maintain a certain amount of TLR3 in the cell membrane in order to identify the extracellularly present viral dsRNA in case of a viral infection." (PMID 33597952, 2020). "TLR3 recognizes a synthetic double-stranded RNA (dsRNA) analog, polyinosinic:polycytidylic acid (poly(I:C)), and promotes the production of both inflammatory cytokines and type I interferon as an antiviral response, thus serving an important role in preventing virus infection." (PMID 32824595, 2020). "Innate immunity acts as the first line of host defense against virus infection by recognizing NDV infection via pattern recognition receptors (PRRs) like RIG-I (retinoic-acid inducible gene I), MDA5 (melanoma differentiation-associated), and TLR3 (Toll-like receptor 3)." (PMID 31396181, 2019). "Therefore, given the pivotal role of TLR3-induced ROS generation and downstream inflammatory responses in corneal epithelium injury post virus infection, therapeutics targeting this important step may benefit in efficiently attenuating HSK progression." (PMID 31889912, 2019). "However, human DCs stimulated with TLR3 agonist plus TSLP favor Th17 cells differentiation, suggesting that viral infections acting through TLR3 stimulation of DCs might favor Th17 cell development and neutrophilic inflammation of asthmatic patients." (PMID 29867994, 2018). "Thus, such a cross-regulation among PRRs (TLR2 and TLR3) causing subsequent downregulation of TLR3 and TICAM1 may result in weakened innate immunity against viral infections." (PMID 29449840, 2018). "Poly-ICLC is one TLR3 agonist which is often combined with vaccine and cellular immunotherapies in order to induce type I interferons and mimic inflammatory response to systemic viral infection by amplification of interferons alpha and gamma as well as IL-1a and IL-6." (PMID 29157306, 2017). "Thus, up-regulation of TLR3 may contribute to an increased lung immune response to viral infection following a bacterial infection." (PMID 28198368, 2017). "Thus, increasing our understanding of how PRRs such as TLR3 are activated and regulated in immune cells and IECs may help designing effective therapies for the prevention and/or treatment of viral diseases." (PMID 27994593, 2016).